DND1 (DND microRNA-mediated repression inhibitor 1)
Diseases named in the same sentence as DND1 in open-access papers (continued):
Sharing a sentence is not in itself a finding about the gene and the disease.
melanoma (1 paper, 2024). A malignant, usually aggressive tumor composed of atypical, neoplastic melanocytes. "Therefore, in this research process, we conducted a more comprehensive exploration of the role and related regulatory mechanism of DND1, which was found to be associated with circular RNA in the progression of melanoma." (PMID 38311675, 2024). "Our findings reveal that circFCHO2 drives melanoma progression by regulating the PI3K/AKT signaling pathway through direct binding to DND1 and may serve as a potential diagnostic biomarker and therapeutic target for the treatment of melanoma." (PMID 38311675, 2024). "To verify our conjecture based on the results of bioinformatics analysis, we proceeded to examine the regulatory impact of DND1 on the in vitro proliferation of melanoma cells." (PMID 38311675, 2024). "It indicated that melanoma patients with low DND1 expression levels had a significantly shorter overall survival period compared to those with high DND1 expression levels." (PMID 38311675, 2024). "Overall, these findings indicate a physical interaction between circFCHO2 and DND1 in melanoma cells." (PMID 38311675, 2024). "Our findings highlight the involvement of circFCHO2 in the regulation of the PI3K/AKT signaling pathway through its interaction with DND1, consequently fostering melanoma proliferation." (PMID 38311675, 2024). "The results demonstrated that the overexpression of DND1 in melanoma cell lines had an inhibitory effect on the in vitro proliferation, invasion, and migration phenotype of melanoma cells, as well as on the activation of the PI3K/AKT signaling pathway induced by the overexpression of circFCHO2." (PMID 38311675, 2024). "So far, we can tentatively confirm that DND1 inhibits the PI3K/AKT signaling pathway in melanoma." (PMID 38311675, 2024). "To investigate whether DND1 and circFCHO2 affect the biological function of melanoma, we further investigated the biological function of DND1 in melanoma." (PMID 38311675, 2024). "It is speculated that DND1 might function as an inhibitory molecule in the progression of melanoma." (PMID 38311675, 2024). "Thus, we can conclude that overexpression of DND1 can restore the promoting effect of overexpression of circFCHO2 on melanoma progression, and confirm that circFCHO2 can promote melanoma progression by combining with DND1 to remove the inhibition of PI3K/AKT signaling pathway." (PMID 38311675, 2024). "Therefore, we speculate that DND1 may be a molecule that plays a significant inhibitory role in melanoma progression." (PMID 38311675, 2024). "Since the correlation between DND1 and melanoma has not been reported yet, we first analyzed the clinical correlation between DND1 and melanoma patients through TCGA database bioinformatics." (PMID 38311675, 2024). "Compared with the control group, the expression of pAKT increased in the DND1 knockdown group, while the total expression of AKT did not change significantly, indicating that DND1 knockdown upregulated the PI3K/AKT signaling pathway in melanoma cells." (PMID 38311675, 2024). "According to the previous research reports, DND1 can regulate PI3K/AKT, TGF, WNT, and other signaling pathways and play a role in relevant evidence; we speculate that the effect of DND1 on the biological function of melanoma may also be achieved by regulating the PI3K/AKT signaling pathway." (PMID 38311675, 2024).
ovarian teratoma (1 paper, 2021). A non-seminomatous germ cell tumor arising from the ovary. "More strikingly, in the WKY/Ztm rat strain, homozygous mutation in Dnd1 led to formation of congenital testicular and ovarian teratomas, as well as infertility with complete penetrance in both genders." (PMID 34359581, 2021). "In addition to TGCTs, DND1 has also been shown to potentially impact ovarian teratomas (OTs) and somatic tumors." (PMID 34359581, 2021).
seminoma (1 paper, 2015). A radiosensitive malignant germ cell tumor found in the testis (especially undescended), and extragonadal sites (anterior mediastinum and pineal gland). "From them, EC-, pluripotency- and reprogramming-associated genes REX1 (ZFP42), DND1, JARID2 and PRDM14 were hypomethylated and upregulated, while seminoma-related genes PRDM1, PROM1 and IGF1 became hypermethylated and were downregulated." (PMID 26226633, 2015).
viral diseases (1 paper, 2016). "The Arabidopsis dnd1 mutant was previously reported to be resistant to bacterial, fungal and viral diseases." (PMID 26577903, 2016).
tumor (11 papers, 2011 to 2024). "High-level expression of DND1 was associated with tumor progression and poor clinical prognosis." (PMID 34721738, 2021). "And to examine whether Dnd1 levels were associated with tumor aggressive character, Dnd1 mRNA level was determined in five cell lines (67NR, 168FARN, 4TO7, 66cl4, and 4T1) with unique tumorigenic feature and increased metastatic capability in order." (PMID 28191469, 2017). "The expression of DND1 in tumor tissues was higher than in paracancerous tissues as shown by using statistical analysis (P < 0.001)." (PMID 34721738, 2021). "In summary, different studies on DND1 function found that DND1 is an anti-proliferative, pro-apoptotic tumor suppressor in a variety of cancers, but may also exert oncogenic function in others." (PMID 34359581, 2021). "The tumor-suppressive function of DND1 in HCC may at least partially result from Hippo signaling activation." (PMID 34359581, 2021). "Furthermore, DND1 acts as a tumor suppressor by restraining CSC-like characteristics by activating the Hippo pathway in HCC cells." (PMID 34721738, 2021). "Therefore, we postulate that Dnd1 is an essential factor involved in teratocarcinogenesis and acts as a tumor suppressor gene in germ cells of the WKY/Ztm rat strain." (PMID 22655094, 2012). "OGCTs developed in all homozygous Dnd1-deficient female rats, whereas no tumor development has been observed in female mice." (PMID 22655094, 2012). "However, additional investigation is required to ascertain whether DND1 is specifically expressed aberrantly in these malignancies or induced by certain stress responses within tumor cells." (PMID 38311675, 2024). "Furthermore, studies on human cell lines, patient cancer tissues, and the use of human cancer genome analysis indicate that DND1 may possess either tumor-suppressive or -promoting functions in a variety of somatic cancers." (PMID 34359581, 2021). "Should the rat mirror the situation in the mouse, it would signify that either Dnd1 target genes differ between females and males or that the downregulation of some cell cycle inhibitors might be a secondary effect and not the primary cause of tumor development." (PMID 22655094, 2012).
cancer (7 papers, 2008 to 2024). A tumor composed of atypical neoplastic, often pleomorphic cells that invade other tissues. "Several studies have unveiled and clarified the molecular mechanisms associated with the function of DND1 and its regulatory role in human malignant tumors." (PMID 38311675, 2024). "It is imperative to further explore the role of DND1 in these cancer types as to whether the changes in DND1 represent passenger events or whether DND1 directly contributes to cancer susceptibility and progression." (PMID 34359581, 2021). "In contrast to the cancer cell line studies and cancer genome data analysis, in vivo model systems allow control of genetic background and testing of direct causal relationship, and thus will serve as important tools for elucidating the possible roles of DND1 in somatic cancers." (PMID 34359581, 2021). "In this study, we found that there was a difference in the mRNA level of DND1 between PCa tissues and adjacent prostate tissues in the cancer genome map (TCGA) dataset by bioinformatics analysis." (PMID 34721738, 2021). "Here we review studies that have investigated mechanisms of DND1 function in vertebrates and especially its role in somatic cancers, including human cancers." (PMID 34359581, 2021). "Overall, these studies indicate that the occurrence of cancer is related to the function and content of microRNA and DND1-mediated mRNA, and the content of mRNA is regulated by the competitive inhibition of microRNA and DND1." (PMID 34721738, 2021). "The goal of this review is to summarize the literature on the role of DND1 in cancers to obtain perspective regarding future scientific endeavors on DND1 function." (PMID 34359581, 2021). "By altering the expression of the Dead-End Homolog Protein 1 (DND1), miR-24 assists in the proliferation of cancer cells and apoptosis escape in TSCC." (PMID 34946938, 2021). "The story of Dead-End 1 (DND1) in cancer of mouse germ cells can be traced back almost half a century." (PMID 34359581, 2021). "Here we review the involvement of DND1 in cancers, including what appears to be its emerging role in somatic cancers." (PMID 34359581, 2021). "Unexpectedly, some recent reports indicate that DND1 may also participate in human cancer development in cells other than those of the testes and ovaries." (PMID 34359581, 2021). "However, contrary to these studies, some findings showed that the expression of DND1 in some tissues will inhibit cell proliferation and metastasis and prevent the occurrence of cancer." (PMID 34721738, 2021). "In addition, we found high DND1 alteration frequency (>5%) in other three cancer types: lung (up to 18.75%), prostate adenocarcinoma (up to 6.49%), and kidney renal clear cell carcinoma (up to 14.12%)." (PMID 34359581, 2021). "Introduction of these DND1 deleted or overexpressing alleles into mouse models for different cancer types will be highly informative to determine whether and how DND1 deletion or overexpression affects somatic cancers." (PMID 34359581, 2021). "Indeed, DND1 plays an essential role during oncogenesis and cancer progression." (PMID 34721738, 2021). "The presence of different repertoires of mRNA/protein in different cells or tissues may account for the opposite roles of DND1 detected in the cancer studies, as DND1 stabilizes some mRNAs but suppresses or degrades others, and can also modify the activity of target protein." (PMID 34359581, 2021). "These patterns of alteration in DND1 and MC4R were specific for TGCTs among patterns of alteration found in various cancers." (PMID 37127675, 2023). "DND1 gene shows minimal alteration in these cancer types that we analyzed (data not shown), except that it is altered, mostly through deletion, in 9.38% of melanomas." (PMID 34359581, 2021).
infection (3 papers, 2016 to 2018). The state of being infected such as from the introduction of a foreign agent such as serum, vaccine, antigenic substance or organism. "It is, therefore, worthwhile to investigate relative expression of SA, ET and JA pathway marker genes in DND1 well-silenced potato and tomato plants in order to understand the impact of DND1 silencing on the pathogen’s infection process." (PMID 29212470, 2017). "In another class of autoimmune mutants, including dnd1 and dnd2, gene-for-gene resistance is normal, but there is almost no HR following infection by avirulent bacterial pathogens." (PMID 30131819, 2018). "Both dnd1 and dnd2 accumulate high levels of SA in the absence of pathogen infection, which is likely responsible for the lack of ETI-induced HR in these mutants." (PMID 30131819, 2018).
prostate (1 paper, 2021). "To explore whether DND1 mRNA expression level is linked with disease-free survival and overall survival in prostate patients, we used the Kaplan-Meier curve method to analyze the relationship between them by using TCGA dataset." (PMID 34721738, 2021).
DND1 also shares sentences with these, for which no sentence is quoted: germ cell tumor (5 papers); bacterial infection (1); bone metastasis (1); intestinal cancer (1); intestinal polyp (1); kidney cancer (1); polyp (1); schizophrenia (1); teratocarcinoma (1); testicular cancer (1).